ICAM1 (intercellular adhesion molecule 1)
Diseases named in the same sentence as ICAM1 in open-access papers (continued):
Sharing a sentence is not in itself a finding about the gene and the disease.
tumor (continued). "Moreover, high-ICAM1 groups outperformed stromal cells (p=0.037), tumor cell purity (p=3.8e-10), and immune score (p=5.4e-08)." (PMID 37671167, 2023). "Moreover, we found that ICAM-1 in TNBC cells promotes tumor cells to secrete suPAR, which functions as a chemoattractant for neutrophils." (PMID 37345070, 2023). "Therefore, blocking the expression of ICAM-1 in tumor exosomes can increase the infiltration and activation of CD8+ T cells in tumors and improve the efficacy of immunotherapy." (PMID 37670933, 2023). "ICAM-1 was found to bind to MUC1 at the tumor leading edge, thus promoting cell invasion." (PMID 36868311, 2023). "Moreover, ICAM1-DXd can further enhance the anti-tumor immunity by significantly upregulating the type I interferon signal pathway." (PMID 37717087, 2023). "TGF-β inhibition enhanced the proinflammatory potential of TANs (N1), resulting in an increased expression of proinflammatory cytokines such as TNF-α and CCL3, cytotoxic CD8+ T lymphocyte activation, and direct killing of tumor cells dependent on ROS and the costimulatory molecule ICAM-1." (PMID 37298230, 2023). "In summary, we demonstrated that ICAM-1 and CD11b mediate tumor cell and neutrophil binding." (PMID 37345070, 2023). "Activating LFA-1 on tumor-infiltrating T cells to boost its binding to ICAM-1 could potentially increase tumor-specific T cell recruitment to the TIME." (PMID 37901252, 2023). "As ICAM‐1 levels correlated with ICI therapy's positive outcomes in patients, we investigated whether ICAM‐1 affects ICI‐responsive or ‐resistant phenotypes using several syngeneic mouse tumor models." (PMID 37097643, 2023). "Opposite to their reports, we found that mutant tumor cells proactively reduced ICAM1 and avoided capturing T cells from the outside, which might be another pattern of immune evasion." (PMID 36871040, 2023). "ICAM-1 isoforms differently regulate antigen-specific tumor cell killing by CTLs." (PMID 37732732, 2023). "ICAM-1 has also been used to direct multiple drugs to tumor cells." (PMID 37237555, 2023). "Furthermore, our complementary CRISPR screen showed that activation of ICAM1 expression enhanced tumor killing by CTLs and depletion attenuated CTL killing." (PMID 37732732, 2023). "Moreover, heat can increase blood perfusion to tumours and upregulates the expression of intercellular adhesion molecule-1 (ICAM-1), thus facilitating the infiltration of immune effector cells into tumours." (PMID 37113720, 2023). "Tumor incidence and growth are correlated to ICAM1 expression." (PMID 37671167, 2023). "Consequently, targeting the CX3CL1‐CX3CR1 axis and ICAM‐1 expression is the potential therapeutic goal for ameliorating oral‐related tumours." (PMID 37082943, 2023). "‐Formation of spheroids composed of macrophages and tumor cells through β2 integrin‐ICAM‐1 interactions.‐Production of EGF by macrophages promoted tumor growth by EFGR signaling in tumor cells, triggering VEGF release by tumor cells and autocrine VEGFR signaling." (PMID 36658699, 2023). "This upregulation of ICAM1 may promote immune cell recruitment and facilitate the anti-tumor immune response." (PMID 37671167, 2023). "The CT26 tumor volume upon anti‐PD‐1 treatment was diminished by ICAM‐1 depletion." (PMID 37097643, 2023). "Therefore, RT potentially activates CD8+ T cells by inducing IFNs-mediated CXCL10 and ICAM-1 expression in tumors to enhance CD8+ T-tumor adhesion and recognition." (PMID 36688994, 2023). "We next evaluated the tumor specificity and biodistribution of ICAM1 ADCs in vivo." (PMID 37717087, 2023). "Our data suggest that PD-1high CAR-T cells are able to produce more IFNγ than PD-1low CAR-T cells, resulting in robust upregulation of ICAM-1 on target cancer cells, which then supports more stable T cell-tumor cell conjugation formations to improve T cell-mediated killing." (PMID 37388744, 2023).
tumor (continued). "This may be related to the fact that TNBC cells low in ICAM-1 expression inhibits the immune cells’ function in the tumor microenvironment and induce polarization of M2-type macrophages." (PMID 37671167, 2023). "Besides, ICAM1-mediated T-cell gathering in tumor tissue, instead of the draining lymph node, was thought to be a trick that tumor escapes from the immune surveillance through overexpression of ICAM141." (PMID 36871040, 2023). "(C) ICAM1 expression in normal (N) or tumor tissue (T) of 22 different human cancers." (PMID 37732732, 2023). "The expression of ICAM1 is directly proportional to the metastatic potential of the tumor cells." (PMID 37737288, 2023). "The presence of ICAM-1 in the neutrophil-rich region suggests that, early after induction of immunogenic cell death (day 3 of panobinostat exposure), the neutrophils are anti-tumor, N1-polarized, and possibly licensed." (PMID 36672243, 2023). "Moreover, we found that ICAM-1 in TNBC cells promotes tumor cells to secrete soluble urokinase-type plasminogen activator receptor (suPAR), which functions as a chemoattractant for neutrophils." (PMID 37345070, 2023). "In a murine model of melanoma overexpressing IL-12 (B16-IL-12), NKp46+ ILC3 were shown to infiltrate the tumor and mediate the upregulation of ICAM-1 and VCAM-1 adhesion molecules on tumor vessels leading to the generation of a pro-inflammatory microvascular environment." (PMID 37234993, 2023). "Besides, Icam1 overexpression-initiated response to immunotherapy was also observed in the subcutaneous tumor model." (PMID 36871040, 2023). "The expression of the adhesion molecules vascular cell adhesion protein 1 (VCAM1) and intercellular adhesion molecule 1 (ICAM1) is inhibited by dysfunction of the vascular system in tumor tissues, which inhibits the effective infiltration of T cells and magnifies the inhibitory effect." (PMID 38115906, 2023). "Collectively, our findings reveal a new mechanism of CTC–neutrophil cluster formation via ICAM-1-suPAR-CD11b axis-mediated tumor cell and neutrophil binding, which could represent new therapeutic targets for treating metastatic TNBC." (PMID 37345070, 2023). "For instance, aberrant expression of VEGF can prevent the trafficking of tumor-reactive T cells to the tumor site by inhibiting the expression of adhesion molecules, such as intercellular adhesion molecule 1 (ICAM-1) and vascular cell adhesion molecule 1 (VCAM-1) within endothelial cells." (PMID 36357599, 2023). "Consistent with the protein levels of Yap in neutrophils from different tissues, enrichment of Yap on Icam1 loci was the highest in neutrophils from the tumor tissue when compared with those from other tissues including bone marrow, spleen, and peripheral blood." (PMID 36921037, 2023). "Although low for ICAM-1, these tumor cells highly express the integrin α6β4." (PMID 36189315, 2022). "The lower expression of these adhesion molecules, such as vascular cell adhesion molecule-1 (VCMA1) or intercellular adhesion molecule-1 (ICAM1), on the irregular tumor vessel endothelium deteriorates the extravasation of immune cells and is termed endothelial anergy." (PMID 36077730, 2022). "Blockade of ICAM-1 reduced tumor incidence and metastasis in vivo." (PMID 35935577, 2022). "In the absence of TNF-α, bFGF reduces the expression of ICAM1 in the tumour-associated endothelial cells and adhesion of leukocytes to endothelial cells." (PMID 36077754, 2022). "In human tumors, ICAM-1 is expressed in all cell types in the tumor microenvironment." (PMID 35565262, 2022). "Notably, CCL7, TAPBP, and ICAM1 were leading edge genes for all three pathways, and both CCL7 and ICAM1 were also trending up in the 14-day primary tumor proteomic analysis." (PMID 35727842, 2022). "We further verified that ICAM-1 secreted from MTCAFs promoted tumor progression in vivo." (PMID 36016615, 2022).
tumor (continued). "Interestingly, the elimination of Tregs led to the rapid killing of primary tumor cells independently of tumor ICAM-1 expression." (PMID 35911772, 2022). "Inefficient integrin activation upon CAR ligation would be particularly critical in conditions of limited expression of adhesion molecules on the surface of tumor cells, in particular ICAM-1, which is frequently downregulated by cancer cells to evade CD8 T-cell mediated destruction." (PMID 35681548, 2022). "In addition, tumor-derived secretory molecules like VEGF-A contribute to the downregulation of endothelial cell adhesion molecules such as ICAM-1, thereby inhibiting T-cell adhesion to endothelial cells and subsequent infiltration in the tumor." (PMID 35693795, 2022). "Since MHC-I and ICAM-1 are known to be involved in the formation of immunological synapse between APCs and T-cells, we aimed to visualize the interactions between neutrophils and T-cells in regional LNs of tumor-bearing animals." (PMID 35833131, 2022). "The interaction between ICAM-1 and its ligand may facilitate adhesion of tumor cells to the vascular endothelium and promote metastasis subsequently." (PMID 36505809, 2022). "We report a mechanism of DTX resistance in HNSCC mediated by the secretion of IL-1β from macrophages to induce ICAM1 expression, which enhances the stemness of tumor cells and promotes PGCC formation in response to DTX treatment, thereby leading to increased chemoresistance." (PMID 36264639, 2022). "Furthermore, localisation and activation of NK cells are mediated by the lymphocyte-associated protein LFA-1 and vascular lymphocyte function-associated protein VLA-4, as well as the recognition of ICAM1 and VCAM1 on tumour endothelial cells." (PMID 36077754, 2022). "ICAM-1 promotes recognition and destruction of tumor cells by the immune cells." (PMID 36505809, 2022). "Previous studies have shown that tumor cell-induced neutrophil ETs could stimulate immune cells to release inflammatory cytokines, including IL-1, IL-6, ICAM-1, VCAM-1, and E-selectin, leading to tumor growth." (PMID 36325339, 2022). "Whether the promoting effect of Gal-3 on tumor-endothelial adhesion induced by H-EVs was related to ICAM-1 was investigated." (PMID 36386163, 2022). "A second mechanism may be that ICAM-1, as a morphogen, enhances tumor cells attachment to the extracellular matrix by promoting motility in the context of remodeling." (PMID 36505809, 2022). "Given that LFA‐1 and MAC‐1, receptors for ICAM‐1, are mainly expressed in macrophages, we hypothesized sICAM‐1 could act as a chemoattractant for macrophages toward the tumor microenvironment." (PMID 34813169, 2022). "In addition, fibrinogen can also directly bind to the intercellular adhesion molecule-1 (ICAM-1) of endothelial cells to promote tumor cell migration." (PMID 35033080, 2022). "Studies have found that intercellular adhesion molecule-1 (ICAM-1) of tumor cells plays a role in tumor progression by promoting malignant phenotype of cancer cells, activity of angiogenesis/lymphangiogenesis, and macrophage infiltration and is significantly associated with LNM." (PMID 35847584, 2022). "E-selectin, ICAM1 or Clec4g mediate tumor cell adhesion and thus facilitate liver metastasis." (PMID 36496412, 2022). "To further dissect the involvement of tumor ICAM-1 in an antitumor immune response elicited by antitumor CTLs, we next tested if monoclonal effector CTLs specific for the OVA neoantigen introduced into E0771 cells can eliminate these cancer cells in vitro and in vivo in an ICAM-1-facilitated manner." (PMID 35911772, 2022). "For instance, tumor-associated macrophages (TAMs) and neutrophils (TANs) may use their LFA-1 and Mac-1 to bind ICAM-1 on primary tumor cells and thereby facilitate tumor growth and angiogenesis." (PMID 35911772, 2022).
tumor (continued). "ICAM-1, thus, plays a crucial part in physiological processes such as cell signal transmission and activation, cell tissue development and differentiation, immunological response, and pathological processes, for example, tumor metastasis." (PMID 36497444, 2022). "Moreover, the expression of integrin α4β1, which supports communication between tumor cells, stromal cells, and vascular cells by binding with intercellular adhesion molecule-1 (ICAM-1) and vascular cell adhesion molecule-1 (VCAM-1)." (PMID 35203510, 2022). "In addition, we found that ICAM1 expression was negatively correlated with tumor purity in KIRC and positively correlated with the infiltration level of macrophages in KIRC." (PMID 36353618, 2022). "Tumor cell can also use leukocytes as linker cells to adhere to the endothelium by ICAM-1." (PMID 36386163, 2022). "In addition, we investigated their potential to reverse the downregulation of MHC-I, ICAM-1, and B7-2 in these tumor cells and the potential role of drug-induced changes in gammaherpesvirus and ERV3-1 expression on these effects." (PMID 35562811, 2022). "However, when ATO was added to the THP-1–tumor cell coculture system, ICAM1 induction was attenuated in HNSCC cells, suggesting that ATO modulates IL-1β secretion by modulating macrophage function." (PMID 36264639, 2022). "Knock out of ICAM-1 gene in tumor cells led to resistance to BCMA CAR T cells." (PMID 36189315, 2022). "Tumor cells are capable of evading immune cells by releasing immunosuppressive molecules (e.g., interleukin IL-10, transforming growth factor β—TGF-β) or by loss of adhesion molecules such as ICAM-1." (PMID 36498469, 2022). "Moreover, inhibition of glycolysis reduced the expression of ICAM-1 in HUVECs to the adhesion of tumor and endothelial cells." (PMID 36386163, 2022). "The increased ICAM-1 expression might reflect the elevated immunity against tumor cells and ICAM-1 renders tumor cells more sensitive to lymphocyte-mediated lysis." (PMID 36505809, 2022). "Moreover, we show that these inhibitors also upregulate expression of ICAM-1 and B7-2 in the infected tumor cells, which can enable NK killing and enhance sensitization of T-cells to the tumor cells." (PMID 35562811, 2022). "Compared with H-EVs, HGal3-EVs increased the expression of ICAM-1 in MDA-MB-231 cells, suggesting that Gal-3 promoted tumor-endothelial adhesion by increasing the expression of ICAM-1 in H-EVs which could enter tumor cells." (PMID 36386163, 2022). "Hence, increasing IFNγ in the tumor site can be considered a promising strategy to restore CAR T cell-tumor cell interaction through ICAM-1 upregulation." (PMID 35681548, 2022). "The upregulation of ICAM-1 inhibited tumor metastasis in CRC cell lines." (PMID 36505809, 2022). "Firstly, vimentin vaccination upregulates intercellular adhesion molecule (ICAM)-1 expression in the tumor vasculature, which can bind to the leukocyte function-associated antigen (LFA)-1 integrin on leukocytes, facilitating their transmigration into the tumor." (PMID 35681575, 2022). "We next analyzed whether MTCAFs with ICAM-1 knockdown affected the tumor progression and immune environment by using a nude mouse xenograft tumor model (mice, n = 10)." (PMID 36016615, 2022). "The transfection of ICAM-1 into CRC cells inhibited tumor metastasis." (PMID 36505809, 2022). "Biologically, ICAM-1 facilitates tumor development and progression." (PMID 35565262, 2022). "Secondly, a bunch of critical adhesion molecules including vascular cell adhesion molecule 1 (VCAM-1) and intercellular adhesion molecule 1 (ICAM-1) expressed on ECs are significantly down-regulated in newly formed tumor blood vessels, which hampers the adhesion and transmigration of T cells." (PMID 36439137, 2022). "It has been reported that ICAM-1 is a marker of LIHC stem cells in humans and mice and ICAM-1 inhibitors could slow tumor formation and metastasis in mice." (PMID 36482887, 2022).
tumor (continued). "The interaction between ICAM-1 and its ligand may facilitate adhesion of tumor cells to the vascular endothelium and subsequently in the promotion of metastasis." (PMID 36505809, 2022). "The other potential mechanism is that ICAM-1 may play an important role in the tumor microenvironment (TME)." (PMID 36505809, 2022). "Notably, the implanted control E0771 cells maintained their surface ICAM-1 expression in this in vivo tumor growth model." (PMID 35911772, 2022). "Invalidation of ICAM-1 gene in tumor cells led to resistance to BCMA CAR T cells." (PMID 35681548, 2022). "By upregulating ICAM-1, cannabinoids render tumor cells vulnerable to the immune system." (PMID 36437760, 2022). "ICAM-1 expressed by tumor cells may lead to T cell-specific recognition and enhanced T cell adhesion." (PMID 36505809, 2022). "Macrophage secretion of IL-1β was found to induce tumor expression of ICAM1." (PMID 36264639, 2022). "ICAM1 promotes tumor stemness and PGCC formation, thereby reducing the effects of DTX in HNSCC." (PMID 36264639, 2022). "Hence, our results support that metformin mediates upregulation of integrin ligands, i.e. ICAM-1, which allows the effective binding and activity of cytotoxic lymphocytes on tumor cells." (PMID 35079096, 2022). "ICAM-1, an important member of the immunoglobulin superfamily and an adhesion receptor, has been reported to be expressed on the tumor cells and HUVECs to participate tumor-endothelial adhesion." (PMID 36386163, 2022). "The engagement of tumor ICAM-1 and CTL LFA-1 can also facilitate cytokine production by CTLs." (PMID 35911772, 2022). "In addition, increased expression of ICAM1 promotes tumour development by enhancing cancer cell invasion and migration ability." (PMID 33811439, 2021). "Moreover, some reports have demonstrated that the expression of ICAM-1 is positively correlated with a more aggressive tumor phenotype and metastatic potential." (PMID 33731208, 2021). "A similar mechanism mediates extravasation of circulating tumor cells during metastasis, where endothelial ICAM-1 might play a crucial role." (PMID 34299272, 2021). "When measured at 10 h after tumor cell injection, anti-ICAM1 effectively reduced the extravasation and metastatic seeding of MDA-MB-231 cells to the lungs in NSG mice, coupled with decreased metastatic signals in the lung and increased number of CTCs trapped in the circulation." (PMID 34381029, 2021). "Recent studies have found that AFP and ICAM-1 also play an important role in tumor prognosis." (PMID 34696675, 2021). "Concomitantly, the expression of ICAM1 in MAPK10-deficient Huh7-shMAPK10 cell line was significantly lower than in the control Huh7-pLKO cell line, suggesting that the silencing of MAPK10 leads to reduced expression of ICAM1 in HCC tumor cell context (P = 0.0401)." (PMID 34408980, 2021). "Additionally, tumor cells upregulate the ligand enothelin-1 in ovarian cancer, which in turn binds to endothelin B receptor on tumor ECs, resulting in the inhibition of ICAM1 expression thus preventing lymphocyte infiltration." (PMID 34987525, 2021). "By determining individual CAR and ICAM-1 expression patterns on tumor biopsies of patients, a pre-selection for one of the viruses might be possible." (PMID 33919076, 2021). "Among them, the neutrophil Mac-1 interaction with tumor ICAM-1 and the neutrophil L-selectin interaction with tumor-cell sialomucins were found to be involved in the neutrophil-mediated capturing of circulating tumor cells resulting in increased metastatic seeding." (PMID 34572138, 2021). "The study showed ICAM-1 involvement in the dissociation and migration of tumour cell aggregates." (PMID 34085677, 2021). "Moreover, platelet depletion and ICAM‐1 knockout inhibited tumor metastasis and vascular permeability in mice after insufficient RFA." (PMID 33643788, 2021). "Importantly, anti-ICAM1 neutralizing antibody as proof-of-concept inhibits cell aggregation, tumor cell TEM, and metastasis in TNBC." (PMID 34381029, 2021).